E4F1 (E4F transcription factor 1)
Description:
May function as a transcriptional repressor. Functions in cell survival and proliferation through control of the cell cycle. Identified as a cellular target of the adenoviral oncoprotein E1A, it is required for both transcriptional activation and repression of viral genes.
Synonyms: E4F
Tractability: PROTAC: UniProt records ubiquitination sites on it; ubiquitination databases record sites on it; its protein half-life has been measured.
Gene: Protein-coding gene on chromosome 16 (2,223,440 to 2,235,743, forward strand). Ensembl gene ENSG00000167967.
Subcellular location: Nucleus, nucleoplasm; Cytoplasm
Subcellular location (Human Protein Atlas): Nucleoplasm
Gene Ontology:
Molecular function: cAMP response element binding; DNA-binding transcription activator activity, RNA polymerase II-specific; DNA-binding transcription repressor activity, RNA polymerase II-specific; protein binding; RNA polymerase II transcription regulatory region sequence-specific DNA binding; RNA polymerase II-specific DNA-binding transcription factor binding; DNA-binding transcription factor activity; RNA polymerase II cis-regulatory region sequence-specific DNA binding; DNA binding; ubiquitin protein ligase activity
Biological process: negative regulation of transcription by RNA polymerase II; positive regulation of transcription by RNA polymerase II; regulation of cell cycle process; regulation of cell cycle; regulation of transcription by RNA polymerase II; protein ubiquitination
Cellular component: nucleoplasm; nucleus; cytoplasm; spindle
Genetic constraint (gnomAD): Loss-of-function variants: 28 observed, 60.15 expected, observed/expected ratio (o/e) 0.47, 90% interval 0.34 to 0.64. The synonymous counts are far from expectation, so gnomAD's model fits this gene poorly and the ratio says little. Missense variants: 1,056 observed, 1,014.1 expected, observed/expected ratio (o/e) 1.04, 90% interval 0.99 to 1.1. Synonymous variants: 523 observed, 436.97 expected, observed/expected ratio (o/e) 1.2, 90% interval 1.11 to 1.29.
Homologues: Orthologues: chimpanzee E4F1 (99% identical), macaque E4F1 (92% identical), pig E4F1 (88% identical), mouse E4f1 (88% identical), rat E4f1 (87% identical), guinea pig E4F1 (87% identical), dog E4F1 (84% identical), rabbit E4F1 (83% identical), tropical clawed frog e4f1 (49% identical), zebrafish e4f1 (44% identical). Paralogues in human: ZFAT (19% identical), PRDM15 (18% identical), ZBTB11 (15% identical), ZNF551 (14% identical), ZNF256 (14% identical), ZNF792 (14% identical), ZNF587B (14% identical), ZNF304 (13% identical), ZFY (13% identical), ZNF583 (13% identical), ZFX (13% identical), ZNF418 (13% identical), and 26 more.
Diseases named in the same sentence as E4F1 in open-access papers:
E4F1 is named in the same sentence as 22 diseases in open-access papers, as found by Europe PMC text mining. Sharing a sentence is not in itself a finding about the gene and the disease. The quoted sentences say what the papers report.
breast carcinoma (5 papers, 2022 to 2026). "Antibodies against either E4F1 or IRF2 consistently resulted in loss of A allele-specific protein binding in both melanoma and breast cancer cell lines." (PMID 41542517, 2026). "Knockdown of E4F1 resulted in an increase in CASP8 levels while IRF2 knockdown results in reduction of CASP8 RNA levels in melanoma, breast cancer, and melanocytes, consistent with respective roles for E4F1 and IRF2 as a potential repressor and activator in cells of melanocytic lineage." (PMID 41542517, 2026). "Previous studies have shown that FHL1 binds the oestrogen receptor transcription factor to regulate breast cancer cell growth and that the binding of FHL2 to the transcription factor E4F1 inhibits its transcriptional regulation and promotes cell proliferation." (PMID 36418297, 2022). "Altogether, our data indicate that in breast cancer cells the ATM/ATR-CHK1 signaling pathway and DNA damage-stress response are tightly controlled at the transcriptional and post-transcriptional level by E4F1." (PMID 36012478, 2022).
triple-negative breast carcinoma (3 papers, 2022 to 2025). An invasive breast carcinoma which is negative for expression of estrogen receptor (ER), progesterone receptor (PR), and human epidermal growth factor receptor 2 (HER2). "Here we identified the transcriptional program directly controlled by E4F1 in Human triple-negative breast cancer (TNBC) cells." (PMID 36012478, 2022). "Here, combining ChIP-Seq and RNA-Seq approaches, we identified the transcriptional program directly controlled by E4F1 in Human Triple-Negative Breast Cancer cells (TNBC)." (PMID 36012478, 2022).
cervical squamous cell carcinoma (1 paper, 2023). A squamous cell carcinoma arising from the cervical epithelium. "It contained 11 prognostic genes of M33 in cervical squamous cell carcinoma (CESC), including the cell-cycle repressor E4F1 and the cytosolic iron–sulfur protein assembly component CIAO3 (previously known as NARFL)." (PMID 37907329, 2023).
disc degeneration (1 paper, 2022). "However, the roles of E4F1 in disc degeneration and NPC senescence remain unclear." (PMID 35340126, 2022).
Glucose intolerance (1 paper, 2021). Glucose intolerance (GI) can be defined as dysglycemia that comprises both prediabetes and diabetes. "Similar to E4f1(aP2)KO mice, E4f1(adipoQ)KO animals exhibited insulin resistance and glucose intolerance." (PMID 34857760, 2021).
Insulin resistance (1 paper, 2021). Increased resistance towards insulin, that is, diminished effectiveness of insulin in reducing blood glucose levels. "While E4F1 expression is upregulated during obesity, E4f1 inactivation in mouse adipose tissue results in a lean phenotype associated with insulin resistance and protection against induced obesity." (PMID 34857760, 2021). "The atypical metabolic profile of mice lacking E4F1 in adipose tissue was associated with insulin resistance despite these animals exhibited diminished adiposity, decreased circulating FFAs but no liver steatosis." (PMID 34857760, 2021).
Leigh syndrome (1 paper, 2021). A progressive neurological disease defined by specific neuropathological features associating brainstem and basal ganglia lesions. "Another striking illustration of the importance of these metabolic activities in human diseases is the recent identification of Leigh syndrome patients harboring a homozygous mutation in the E4F1 gene." (PMID 33406607, 2021). "Indeed, a non-synonymous homozygous mutation (K144Q) in the coding region of the human E4F1 gene was recently identified in two siblings of an Italian family presenting clinical symptoms reminiscent of those of Leigh syndrome patients." (PMID 33406607, 2021).
lung carcinoma (1 paper, 2018). "The following literature review confirmed that six of the nine TFs, including E2F8, MEIS, E4F1, BRCA1, GATA6, and IRX2, play essential roles in lung cancer progression." (PMID 29303984, 2018).
melanoma (1 paper, 2026). A malignant, usually aggressive tumor composed of atypical, neoplastic melanocytes. "In particular, we identified proteins that typically act either as a transcriptional repressor (E4F1) or activator (IRF2) as both preferentially binding the A-risk allele of rs3769823, and verified binding of both factors via ChIP in melanoma cells and primary melanocytes." (PMID 41542517, 2026). "Indeed, gene expression correlation analyses suggest, for example, that E4F1 may play a prominent role for CASP8 regulation in melanocytes, while the activator IRF2 may play a larger role in regulation of CASP8 in melanomas." (PMID 41542517, 2026).
microcephaly (1 paper, 2025). A congenital or acquired developmental disorder in which the circumference of the head is smaller than normal for the person's age and sex. "Our data indicate that perturbation of E4F1 activities during embryonic development results in severe brain defects and microcephaly associated to impaired tRNAs U34 modifications, translation defects and the induction of an integrated stress response (ISR) leading to neuronal cell death." (PMID 39747033, 2025).
Obesity (1 paper, 2021). Accumulation of substantial excess body fat. "The reduced adiposity of E4f1(aP2)KO mice prompted us to determine their resistance to induced obesity." (PMID 34857760, 2021). "When challenged on a high-fat diet (HFD), E4f1(aP2)KO mice displayed resistance to diet-induced obesity." (PMID 34857760, 2021). "Altogether, these results support an important role for E4F1 in obesity." (PMID 34857760, 2021).
osteosarcoma (1 paper, 2014). A usually aggressive malignant bone-forming mesenchymal neoplasm, predominantly affecting adolescents and young adults.
cancer (9 papers, 2018 to 2023). A tumor composed of atypical neoplastic, often pleomorphic cells that invade other tissues. "E4F1 has a critical role in cancer cell survival and could be a target for cancer therapy." (PMID 29303984, 2018). "For instance, the up-regulation of ZNF148 following knockdown of all other factors, including E4F1, could be a compensatory mechanism to up-regulate TERT expression, which is vital for unlimited cancer cell proliferation." (PMID 37918959, 2023). "Cancer cells lacking E4F1 is arrested in G2/M of cell cycle." (PMID 32962114, 2020).
E4F1 also shares sentences with these, for which no sentence is quoted: myeloid leukaemia (2 papers); adenovirus-infection (1); asthma (1); colon carcinoma (1); diabetes (1); intervertebral disc degeneration (1); metabolic disease (1); sarcoma (1); tumor (1).